WHR1 (winged helix repair factor 1)
Description:
DNA-binding protein which is required for efficient transcription-coupled nucleotide excision repair (TC-NER). Acts as part of a TC-NER complex which assembles and interacts with RNA polymerase II (RNAPII) when it stalls at DNA lesions. TC-NER complex subunit UVSSA binds to the GTF2H1/p62 subunit of the TFIIH transcription factor complex, tethering TFIIH to the TC-NER complex. WHR1/STK19 then interacts with the XPD helicase subunit of TFIIH which guides TFIIH to DNA downstream of the stalled RNAPII, ensuring DNA repair. Directly interacts with RNAPII and also binds to downstream DNA. Promotes the timely removal of DNA damage-stalled RNAPII, allowing downstream NER factors to access DNA lesions. Required for monoubiquitination of UVSSA. Regulates repositioning and stabilization of UVSSA within the TC-NER complex. Stimulates ubiquitination of RNAPII complex member RBP1. Also binds to RNA and regulates the expression levels of many mRNAs.
Synonyms: G11; RP1; STK19; TWH19; D6S60; D6S60E; HLA-RP1
Tractability: Small molecule: a structure with a bound ligand is known; a high-quality ligand is known. PROTAC: ubiquitination databases record sites on it; a small molecule that binds it is known.
Target class: Enzyme; Transferase
Gene: Protein-coding gene on chromosome 6 (31,971,091 to 31,982,821, forward strand). Ensembl gene ENSG00000204344.
Subcellular location: Nucleus (Isoform 4); Nucleus (Isoform 3); Nucleus (Isoform 1); Cytoplasm
Subcellular location (Human Protein Atlas): Nuclear speckles
Gene Ontology:
Molecular function: double-stranded DNA binding; double-stranded RNA binding; protein binding; protein homodimerization activity; protein serine/threonine kinase activity
Biological process: positive regulation of Ras protein signal transduction; positive regulation of single strand break repair
Cellular component: cytoplasm; nuclear speck; nucleus
Genetic constraint (gnomAD): Loss-of-function variants: 23 observed, 31.1 expected, observed/expected ratio (o/e) 0.74, 90% interval 0.53 to 1.05. The synonymous counts are far from expectation, so gnomAD's model fits this gene poorly and the ratio says little. Missense variants: 285 observed, 317.72 expected, observed/expected ratio (o/e) 0.9, 90% interval 0.81 to 0.99. Synonymous variants: 102 observed, 133.83 expected, observed/expected ratio (o/e) 0.76, 90% interval 0.65 to 0.9.
Homologues: Orthologues: chimpanzee STK19 (99% identical), macaque STK19 (97% identical), pig STK19 (89% identical), guinea pig WHR1 (88% identical), rabbit WHR1 (87% identical), mouse Stk19 (86% identical), rat Stk19 (70% identical), zebrafish stk19 (52% identical), zebrafish WHR1 (52% identical), tropical clawed frog whr1 (50% identical).
Diseases named in the same sentence as WHR1 in open-access papers:
WHR1 is named in the same sentence as 25 diseases in open-access papers, as found by Europe PMC text mining. Sharing a sentence is not in itself a finding about the gene and the disease. The quoted sentences say what the papers report.
melanoma (21 papers, 2015 to 2025). A malignant, usually aggressive tumor composed of atypical, neoplastic melanocytes. "An excellent example to illustrate this concept are the mutations in the winged helix repair factor 1 (WHR1; better known as STK19) that are detected in 5% of melanoma tumors." (PMID 41278537, 2025). "The winged helix repair factor 1 (WHR1, previously known as STK19) c.265G>A (GenBank: NM_004197.1) (p.Asp89Asn) mutation is another example of a misannotated gene-promoter mutation in melanoma." (PMID 40359938, 2025).
WHR1 also shares sentences with these, for which no sentence is quoted: cancer (10 papers); schizophrenia (4); uveal melanoma (4); depression (3); autoimmune disease (2); tumor (2); allergic disease (1); Arthritis (1); asthma (1); atherosclerosis (1); autoimmune disorders (1); Cockayne syndrome (1); congenital adrenal hyperplasia (1); diabetes (1); digestive system cancer (1); epilepsy (1); familial melanoma (1); metabolic syndrome (1); Obesity (1); osteosarcoma (1); prostate carcinoma (1); rheumatoid arthritis (1); UV-sensitive syndrome (1); viral infections (1).